PGR (progesterone receptor)
Diseases named in the same sentence as PGR in open-access papers (continued):
Sharing a sentence is not in itself a finding about the gene and the disease.
breast cancer (continued). "To gain further insight into the relationship of ESR1 and PGR expression, we performed a scatterplot of ESR1 and PGR mRNA expression levels across 4,111 breast cancers." (PMID 23971947, 2013). "The expressions of steroid hormone receptors such as estrogen receptor (ER) and progesterone receptor (PR), and the oncogene ErbB-2/human epidermal growth factor receptor 2 (HER-2) are important factors in distinguishing breast cancer subtypes." (PMID 23476649, 2013). "Multivariable analyses using the LASSO revealed that expression of PGR, ESR1, NAT1, GABRP, TBC1D9, SLC39A6 and LRBA of the 32 gene candidates was collectively the most important predictors for both breast cancer mortality and recurrence." (PMID 23819905, 2013). "The panel of 21 genes in Oncotype DX includes some well-known biomarker genes for breast cancer subtypes and prognosis prediction such as Ki67, HER2, ER, and PGR." (PMID 23383020, 2013). "For other ER-induced markers such as progesterone receptor (PGR) and growth regulation by estrogen in breast cancer 1 (GREB1), the addition of MPA blocked 75% and 71% of CEE-induced expression, respectively." (PMID 23938070, 2013). "The gene cluster included TFF1, PGR, GREB1, and other ER-sensitive genes such as insulin-like growth factor binding protein 1 (IGFBP1), breast carcinoma amplified sequence, and fibulin." (PMID 23938070, 2013). "Our patient cohort included early breast cancer patients with high-risk characteristics: half were premenopausal, the majority had ≥4 positive axillary lymph nodes, large tumor size in most cases, almost half had high grade tumors, while 18.5% had ER/PgR-negative and 21.8% HER2-positive tumors." (PMID 23146280, 2012). "We investigated the status of estrogen receptor alpha (ERα), progesterone receptor (PR), and epidermal growth factor receptor 2 (HER2) in primary tumor and in the corresponding brain metastases in a consecutive series of breast cancer patients." (PMID 22898337, 2012). "We then constructed a population of 4T1 breast cancer cells to mimic the TPBC phenotype in humans, and that are phenotypically HER2+/ER+/PgR+." (PMID 22452810, 2012). "Breast cancers that are “triple-negative” for the clinical markers ESR1, PGR, and HER2 typically belong to the Basal-like molecular subtype." (PMID 23173005, 2012). "The presence of estrogen receptor (ER), progesterone receptor (PR) and human epidermal growth factor receptor 2 (Her2, also known as ERBB2) is routinely reported in the pathological assessment of breast cancer." (PMID 21939527, 2011). "Several initiatives have been introduced to provide guidelines for testing the adequacy of the routine biomarker tests (that is, oestrogen receptor (ER), progesterone receptor (PR) and human epidermal growth factor receptor 2 (HER2) tests) in breast cancer." (PMID 21504565, 2011). "RNA in situ hybridization (ISH) and immunohistochemical (IHC) staining for AIB1, IHC staining for ER and the progesterone receptor (PR) and IHC staining and silver in situ hybridization (SISH) for HER2 were performed for 185 breast cancer cases." (PMID 22035181, 2011). "Tumour size, axillary lymph node involvement, grade as defined by Elston & Ellis, Estrogen Receptor (ER) status, Progesterone Receptor (PR) status and HER2 status are routine determinants of the breast cancer prognosis." (PMID 22087319, 2011). "Genes of known importance in breast cancer and estrogen signaling, including ERBB2, PGR, MYC, CLU, and NCOA2, were among those identified as Sin3A-responsive." (PMID 20920219, 2010). "No predictive factors except the progesterone receptor status were associated with the risk of developing a new second primary cancer other than breast carcinoma, but a poor statistical power may explain these results (only 30 new second primary cancers were observed)." (PMID 21194468, 2010).
breast cancer (continued). "Cheang reported that the expanded surrogate of PgR, HER2, EGFR, and cytokeratin 5/6 indicate a more specific definition of basal-like breast cancer, mostly TNBC, which better predicts breast cancer survival." (PMID 19534825, 2009). "ER, PgR, and HER2 are widely used and should be determined in every patient with early breast cancer." (PMID 19156146, 2009). "In breast cancer, a variety of critical genes have been shown to be silenced by methylation (e.g., BRCA1, 14-3-3, TIM3, ESR1, PGR and E-cadherin)." (PMID 19267929, 2009). "Immunohistochemical analysis of cyclins A, B1, D1 and E, estrogen receptor, progesterone receptor, Ki-67, Her-2/neu and CK5/6 was performed on 53 breast carcinomas." (PMID 19615042, 2009). "In our study, patients with BRCA1 gene mutations were tested for the expression of steroid receptors (ERβ, ERα and PgR) and the HER-2 receptor in breast cancer tissue." (PMID 18405391, 2008). "It was recently shown that Wnt1 is induced by progesterone receptor (PgR) signaling in T47D breast cancer cells and that it is required for EGFR transactivation by a PgR agonist in an Src- and metalloprotease-dependent manner." (PMID 17897439, 2007). "Our study demonstrates that expression levels of ER, progesterone receptor, ERBB2 and other genes relevant for the management of breast cancer as detected in CBs are representative for the whole tumor." (PMID 16919157, 2006). "In addition, associating irradiation and letrozole may modify the cytosolic oestrogen and progesterone receptor content in breast cancer cells, which might explain the observed changes in these cells' radiation sensitivity during hormonal treatment, as published with TAM." (PMID 15642164, 2005). "In breast cancer, METTL16 expression correlates with estrogen receptor (ER) and progesterone receptor (PR) levels, indicating that it may play different roles in various breast cancer subtypes." (PMID 41459114, 2026). "Triple-negative breast cancer (TNBC) is among the most aggressive breast cancer subtypes, characterized by the absence of estrogen receptor, progesterone receptor, and HER2 expression." (PMID 41495194, 2026). "Triple-negative breast cancer (TNBC) accounts for 10–20% of all breast cancers and is characterized by the absence of estrogen receptor, progesterone receptor, and HER2 amplification, leading to poorer prognoses compared to other subtypes." (PMID 41516402, 2026). "Conventionally, breast cancer diagnosis involves evaluating the presence or absence of three receptors: ER, Progesterone Receptor (PR), and HER2." (PMID 40913401, 2026). "Triple-negative breast cancer (TNBC) is one of the most aggressive and clinically challenging subtypes of breast cancer, defined by the absence of estrogen receptor, progesterone receptor, and human epidermal growth factor receptor 2 expression." (PMID 42121910, 2026). "Triple-negative breast cancer (TNBC) is an aggressive and clinically challenging subtype of breast cancer characterized by the absence of estrogen receptor, progesterone receptor, and HER2 expression." (PMID 41681885, 2026). "Triple-negative breast cancer (TNBC) remains one of the most aggressive and therapeutically challenging breast cancer subtypes, lacking expression of estrogen receptor, progesterone receptor, and HER2." (PMID 41749871, 2026). "Triple-negative breast cancer (TNBC), defined by the absence of estrogen receptor (ER), progesterone receptor (PR) and human epidermal growth factor receptor 2 (Her2), constitutes approximately 15-20% of all breast cancer (BRCA) cases." (PMID 40475010, 2025). "Triple-negative breast cancer (TNBC) is a particular form of breast cancer distinguished by the lack of three significant receptors: estrogen receptor (ER), progesterone receptor (PR), and human epidermal growth factor receptor 2 (HER2)." (PMID 40284417, 2025).
breast cancer (continued). "A correlation was also reported between PARP1 and BRCA1/2, and at the same time, with ERBB2 and PGR in the luminal B subgroup; such results can indicate that those breast cancer patients can receive Anti-HER2 Monoclonal Antibodies and anti-PGR drugs available in the clinic at present." (PMID 40141415, 2025). "Triple-negative breast cancer (TNBC) accounts for 10–15% of all breast cancers (BC) and is defined by the absence of estrogen receptor (ER), progesterone receptor (PR) and human epidermal growth factor receptor 2 (HER2) expression." (PMID 41316480, 2025). "Similarly, in breast cancer, DEP aids in the identification of critical protein biomarkers including estrogen receptor (ER), progesterone receptor (PR), human epidermal growth factor receptor 2 (HER2), and cancer antigen 27.29 (CA27.29)." (PMID 40428658, 2025). "Triple-negative breast cancers (TNBC) comprise 15% to 20% of all breast cancers and lack key clinical biomarkers [estrogen receptor (ER), progesterone receptor (PR), and HER2] that guide established molecularly targeted treatments for other breast cancer subtypes." (PMID 40019775, 2025). "According to tumoral expression of the estrogen receptor (ER), progesterone receptor (PR), and human epidermal growth factor receptor 2 (HER-2), breast cancer is classified into four molecular subtypes: luminal A, luminal B, HER-2 type, and triple-negative breast cancer (TNBC)." (PMID 39714760, 2025). "This discordance between the primary tumour and metastatic niche for the expression of the receptors ER, PgR, and HER-2 may be as high as 31.5% of breast cancer patients." (PMID 41373503, 2025). "This study also found a predominance of Luminal A and Luminal B (HER2-negative) breast cancer subtypes, emphasizing estrogen and progesterone receptor signaling." (PMID 40941615, 2025). "Triple-negative breast cancer (TNBC) accounts for 15–20% of all breast cancer cases and is characterized by the lack of estrogen receptor (ER), progesterone receptor (PR), and HER2 expression." (PMID 41154395, 2025). "In our study, we retrospectively examined progesterone receptor expression levels in 199 cases of luminal type, Her-2-negative, clinically and radiologically axilla-negative T1-T2 breast cancer." (PMID 40283001, 2025). "In 14 patients (12.3%) with HR+/HER2+ breast cancer was not administered endocrine therapy: in 3 patients due to values of ER and PgR less than or equal to 10% and in other 11 patients due to unexplained causes." (PMID 40270610, 2025). "Late stage at diagnosis, high tumor grade, triple-negative subtype (lacking estrogen receptor, progesterone receptor, and human epidermal growth factor receptor 2 expression), breast cancer–specific death." (PMID 40740869, 2025). "TNBC is characterized by the absence of three receptors commonly found in other breast cancer subtypes: estrogen receptor (ER), progesterone receptor (PR), and human epidermal growth factor receptor 2 (HER2)." (PMID 41261289, 2025). "HER2-positive breast cancers represent 10–15% of all breast cancers, and are estrogen receptor-negative, progesterone receptor-negative, and HER2 receptor-positive." (PMID 40725412, 2025). "The expression of miR-548ao-5p and miR-4804-3p is closely related to clinical features, such as human epidermal growth factor receptor 2 (HER2), estrogen receptor (ER), progesterone receptor (PR), HER2-enriched subtype, stage III/IV, and lymph node-transplanted breast cancer." (PMID 40158122, 2025). "TNBC is characterized by the absence of the three main druggable receptors within breast cancer cells: estrogen receptor (ER), progesterone receptor (PR), and HER2." (PMID 41273720, 2025). "According to the different expression levels of estrogen receptor (ER), progesterone receptor (PR), human epidermal growth factor receptor 2 (HER2) and Ki67, breast cancer could be generally classified into four molecular subtypes." (PMID 40014756, 2025).
breast cancer (continued). "Triple-negative breast cancer (TNBC) is an aggressive type of breast cancer (BC), defined by the absence of estrogen receptor (ER), progesterone receptor (PR), and human epidermal growth factor receptor 2 (HER2)." (PMID 40744919, 2025). "Triple-negative breast cancer (TNBC) is among the most difficult subtypes of breast cancer to treat and is characterized by the absence of estrogen receptor, progesterone receptor, and HER2 expression." (PMID 41014449, 2025). "Triple-negative breast cancer (TNBC) is a subtype of breast cancer characterized by the absence of estrogen receptor (ER), progesterone receptor (PR), and human epidermal growth factor receptor 2 (HER2) expression." (PMID 40718834, 2025). "Breast cancer can be grouped into four different principal types based on the presence or absence of the estrogen receptor (ER), the progesterone receptor (PR), and HER2 (human epidermal growth factor 2-ERBB2)." (PMID 40507272, 2025). "TNBC represents a highly aggressive subtype of breast cancer, distinguished by the lack of estrogen receptor (ER), progesterone receptor (PR), and human epidermal growth factor receptor 2 (HER2) expression." (PMID 41209020, 2025). "Triple-negative breast cancer (TNBC) is a challenging subtype of breast cancer to treat because it lacks the expression of progesterone receptor (PR), estrogen receptor (ER), and human epidermal growth factor receptor 2 (HER2)." (PMID 41229499, 2025). "Triple‐negative breast cancer (TNBC) is a subtype of breast cancer that is characterised by a lack of oestrogen receptor (ER), progesterone receptor (PR), and human epidermal growth factor receptor 2 (HER2) expression." (PMID 40457119, 2025). "A total of 132 biopsy-proven cases of breast cancer that were negative for estrogen receptor (ER), progesterone receptor (PR), and HER/2neu and were administered neoadjuvant chemotherapy before surgery were included in the study." (PMID 40008380, 2025). "The ER-positive luminal cancers represent the most prevalent subtype of breast cancer, with nearly 70% of breast tumours overexpressing ER, with or without the progesterone receptor." (PMID 40275985, 2025). "In addition, discordance rates of ER, PgR, and HER2 expression status have been reported between primary and recurrent breast cancer lesions, and patients who convert to ER-negative status have a poor prognosis." (PMID 41209903, 2025). "Triple negative breast carcinoma (TNBC) represents approximately 10–20% of all breast cancers and is characterized by the absence of estrogen receptor (ER), progesterone receptor (PR), and HER2 expression." (PMID 40864776, 2025). "It is noteworthy that patients with advanced HER2-low breast cancer have traditionally been categorized under triple-negative breast cancer (characterized by the absence of estrogen receptor, progesterone receptor, and HER2 expression)." (PMID 40177129, 2025). "Breast cancers that express no estrogen receptor (ER), progesterone receptor (PR), or HER2 are classified as TNBC." (PMID 40006082, 2025). "TNBC is the most aggressive type of breast cancer, characterized by the absence of estrogen receptor (ER) and progesterone receptor (PR) expression, and lack of human epidermal growth factor receptor 2 (HER2) amplification." (PMID 40649917, 2025). "Triple-negative breast cancer (TNBC) is an aggressive breast cancer subtype characterized by the absence of estrogen receptor, progesterone receptor, and HER2 expression, leading to poor clinical outcomes and resistance to targeted therapies." (PMID 40819077, 2025). "According to the molecular and histological features BC could be divided into the three groups: BCs expressing hormone receptor (ER—estrogen receptor), or (PR—progesterone receptor), BCs expressing HER+ (human epidermal receptor 2) and TNBC (triple-negative breast cancers)." (PMID 40136652, 2025).
breast cancer (continued). "Triple-negative breast cancer (TNBC) is an aggressive form of breast cancer (BC) characterized by the absence of estrogen receptor (ER), progesterone receptor (PR), and human epidermal growth factor receptor 2 (HER2) expression." (PMID 41321870, 2025). "Gallen consensus, breast cancer can be divided into luminal and non-luminal subtypes based on the expression levels of hormone receptors, which are estrogen receptor (ER), progesterone receptor (PR) and human epidermal growth factor receptor (HER2)." (PMID 40308499, 2025). "Among the 244 HER2-negative breast cancer patients, HER2-ultralow tumors showed significantly higher ER positivity compared with HER2-null tumors (51.8% vs. 19.6%, p < 0.001), and also tended to show higher PgR positivity (p = 0.048)." (PMID 41316049, 2025). "TNBC is an aggressive and various subtype of breast cancer, notable by the lack of specific oestrogen receptor (ER), progesterone receptor (PR), and human epidermal growth factor receptor 2 (HER2), consequential in limited treatment options and poor prognosis." (PMID 41477589, 2025). "TNBC, representing 15–20% of all breast cancers, is the most aggressive subtype of BC, characterized by the lack of estrogen receptor (ER), progesterone receptor (PR), and human epidermal growth factor receptor 2 (HER2) expression." (PMID 41463479, 2025). "Triple-negative breast cancer (TNBC) is a biologically aggressive subtype of breast cancer, characterized by the absence of estrogen receptor (ER), progesterone receptor (PR), and human epidermal growth factor receptor 2 (HER2) expression." (PMID 40806559, 2025). "Clinically, based on the expression of hormone receptors: estrogen receptor (ER), progesterone receptor (PR) and HER2 (human epidermal growth factor receptor 2, ERBB2), breast cancer is classified into three major subtypes: Luminal, HER2-enriched and triple-negative breast cancer (TNBC)." (PMID 41372129, 2025). "Triple-negative breast cancer (TNBC) is a breast cancer subtype defined by the absence of progesterone receptor (PR), estrogen receptor (ER), and human epidermal growth factor receptor 2 (HER2)." (PMID 39814550, 2025). "Triple-negative breast cancer (TNBC) is a subtype of breast cancer that is negative for the estrogen receptor, progesterone receptor, and HER2." (PMID 40723905, 2025). "Triple-negative breast cancer (TNBC) is an aggressive subtype of breast cancer characterized by the absence of estrogen receptor, progesterone receptor, and human epidermal growth factor receptor 2, limiting the efficacy of conventional targeted therapies." (PMID 40942060, 2025). "Breast cancer is classified according to the presence or absence of estrogen receptor (ER), progesterone receptor (PR), and human epidermal growth factor receptor 2 (HER2)." (PMID 40422206, 2025). "Although we stained only for ER in this study, a strength of this method is that it could also be applied to PgR, HER2, and Ki-67, which are important biomarkers in breast cancer treatment." (PMID 39941732, 2025). "Similarly, breast cancer subtypes—HER2-positive, Luminal A/B, and Basal-like—require distinct biomarker panels (HER2, estrogen receptor (ER), and progesterone receptor (PR)) to guide treatment selection." (PMID 41006271, 2025). "Triple-negative breast cancer (TNBC), a specific subtype of mammary cancer that is characterized by negative expression of estrogen receptor (ER), progesterone receptor (PR), or human epidermal growth factor receptor 2 (HER-2), is prone to metastasis." (PMID 38273337, 2024). "Breast cancers can also be categorized into different subtypes based on the expression levels of the human epidermal growth factor receptor 2 (HER2) and two hormone receptors: estrogen receptor (ER) and progesterone receptor (PR)." (PMID 38238542, 2024). "TNBC is a special type of breast cancer in which the tumor cells do not contain estrogen receptor (ER), progesterone receptor (PR) and HER2." (PMID 38857504, 2024).